RNU6-1336P (RNA, U6 small nuclear 1336, pseudogene)
Gene: Small nuclear RNA gene on chromosome 4 (168,686,608 to 168,686,716, reverse strand). Ensembl gene ENSG00000206613.
Homologues: Orthologues: chimpanzee U6 (97% identical), macaque U6 (91% identical), dog U6 (80% identical), guinea pig U6 (79% identical). Paralogues in human: RNU6-1316P (89% identical), RNU6-20P (89% identical), RNU6-35P (89% identical), RNU6-434P (89% identical), RNU6-1145P (88% identical), RNU6-16P (88% identical), RNU6-25P (88% identical), RNU6-29P (88% identical), RNU6-38P (88% identical), RNU6-393P (88% identical), RNU6-46P (88% identical), RNU6-1 (87% identical), and 1285 more.